UBE3C (ubiquitin protein ligase E3C)
Description:
E3 ubiquitin-protein ligase that specifically catalyzes 'Lys-29'- and 'Lys-48'-linked polyubiquitin chains. Accepts ubiquitin from the E2 ubiquitin-conjugating enzyme UBE2D1 in the form of a thioester and then directly transfers the ubiquitin to targeted substrates. Associates with the proteasome and promotes elongation of ubiquitin chains on substrates bound to the 26S proteasome. Also catalyzes 'Lys-29'- and 'Lys-48'-linked ubiquitination of 26S proteasome subunit ADRM1/RPN13 in response to proteotoxic stress, impairing the ability of the proteasome to bind and degrade ubiquitin-conjugated proteins. Acts as a negative regulator of autophagy by mediating 'Lys-29'- and 'Lys-48'-linked ubiquitination of PIK3C3/VPS34, promoting its degradation. Can assemble unanchored poly-ubiquitin chains in either 'Lys-29'- or 'Lys-48'-linked polyubiquitin chains; with some preference for 'Lys-48' linkages. Acts as a negative regulator of type I interferon by mediating 'Lys-48'-linked ubiquitination of IRF3 and IRF7, leading to their degradation by the proteasome. Catalyzes ubiquitination and degradation of CAND2.
Synonyms: HectH2; RAUL; KIAA0010; KIAA10; NDSMBA; NEDSMBA
Tractability: PROTAC: UniProt records ubiquitination sites on it; ubiquitination databases record sites on it; its protein half-life has been measured.
Target class: Enzyme; Transferase
Gene: Protein-coding gene on chromosome 7 (157,138,922 to 157,269,372, forward strand). Ensembl gene ENSG00000009335.
Subcellular location (Human Protein Atlas): Cytosol; Lipid droplets; Vesicles
Pathways (Reactome):
Immune System: Antigen processing: Ubiquitination & Proteasome degradation
Gene Ontology:
Molecular function: protein binding; ubiquitin protein ligase activity; ubiquitin-protein transferase activity
Biological process: protein K29-linked ubiquitination; protein K48-linked ubiquitination; protein polyubiquitination; ubiquitin-dependent protein catabolic process; protein ubiquitination
Genetic constraint (gnomAD): Loss-of-function variants: 42 observed, 127.13 expected, observed/expected ratio (o/e) 0.33, 90% interval 0.26 to 0.43. The upper end of that interval is the gene's LOEUF score, 0.43, which puts it in group 1 of 6, group 1 being the genes least tolerant of losing a copy. Missense variants: 1,044 observed, 1,351.1 expected, observed/expected ratio (o/e) 0.77, 90% interval 0.73 to 0.81. Synonymous variants: 509 observed, 506.34 expected, observed/expected ratio (o/e) 1.01, 90% interval 0.93 to 1.08.
Homologues: Orthologues: chimpanzee UBE3C (99% identical), macaque UBE3C (99% identical), rabbit UBE3C (97% identical), dog UBE3C (96% identical), guinea pig UBE3C (93% identical), mouse Ube3c (93% identical), rat Ube3c (93% identical), pig UBE3C (93% identical), tropical clawed frog ube3c (86% identical), zebrafish ube3c (77% identical), Drosophila melanogaster CG3356 (40% identical), Caenorhabditis elegans etc-1 (26% identical). Paralogues in human: UBE3B (28% identical), HECW1 (20% identical), HECW2 (19% identical), HUWE1 (19% identical), WWP2 (17% identical), ITCH (17% identical), WWP1 (16% identical), NEDD4L (16% identical), NEDD4 (16% identical), HECTD4 (16% identical), HACE1 (16% identical), SMURF2 (16% identical), and 12 more.
Diseases named in the same sentence as UBE3C in open-access papers:
UBE3C is named in the same sentence as 35 diseases in open-access papers, as found by Europe PMC text mining. Sharing a sentence is not in itself a finding about the gene and the disease. The quoted sentences say what the papers report.
glioma (5 papers, 2015 to 2021). A benign or malignant brain and spinal cord tumor that arises from glial cells (astrocytes, oligodendrocytes, ependymal cells). "To determine the mechanism underlying UBE3C induction of glioma progression, we performed co-IP experiments followed by MS to determine the UBE3C-interacting proteins in U87, U251, and TJ899 cells." (PMID 26067607, 2015). "In the particular case of gliomas, UBE3C upregulation was found in glioma tissues compared to surrounding normal tissues; its overexpression promoted invasion and mobility of GBM cells." (PMID 33665742, 2021). "Inhibition of UBE3C expression in glioma cells significantly decreased cell migration and invasion in vitro." (PMID 26067607, 2015). "UBE3C mRNA was highly expressed in glioma samples compared to the corresponding adjacent normal samples." (PMID 26067607, 2015). "We found that UBE3C was more highly expressed in glioma tissues compared to adjacent normal tissues, and elevated UBE3C expression resulted in the progression of glioma." (PMID 26067607, 2015). "Another important finding from present study was that UBE3C promoted glioma progression through formation of a complex with ANXA7 and ubiquitination and degradation of ANXA7." (PMID 26067607, 2015). "On one hand, the results support the notion that UBE3C plays an important role in glioma progression." (PMID 26067607, 2015). "A more important finding from our study was that glioma patients with high UBE3C expression had poor prognosis." (PMID 26067607, 2015). "In this study, we confirmed that UBE3C expression was markedly increased in glioma tissues compared to that in adjacent normal tissues." (PMID 26067607, 2015). "IHC assay also showed that UBE3C protein expression positively correlated with low ANXA7 protein expression in glioma tissues, and vice versa." (PMID 26067607, 2015). "In view of the roles of ubiquitin-proteasome pathway in cancer, it will make sense to study the roles and mechanisms of UBE3C in gliomas." (PMID 26067607, 2015). "On the other hand, UBE3C mediating ANAX7 degradation may be used to develop the specific proteasome inhibitor for the treatment of gliomas." (PMID 26067607, 2015). "Thus, our data reveal that high UBE3C expression contributes to glioma progression by ubiquitination and degradation of ANXA7, and thus presents a novel and promising target for glioma therapy." (PMID 26067607, 2015). "We demonstrated that UBE3C was overexpressed in glioma tissues and cell lines." (PMID 26067607, 2015). "Here, we investigated the expression and roles of UBE3C in glioma." (PMID 26067607, 2015). "In the present study, we investigated the roles and mechanisms of UBE3C in glioma." (PMID 26067607, 2015). "Clinically, UBE3C overexpression correlated with poor survival of glioma patients." (PMID 26067607, 2015). "Moreover, UBE3C promotes glioma progression by ubiquitinating and degrading Annexin A734." (PMID 34652890, 2021). "Importantly, the inhibition of ANXA7 expression in gliomas cells with UBE3C interference could rescue the cell invasion." (PMID 26067607, 2015). "This suggests that UBE3C may be a promising prognostic biomarker for gliomas." (PMID 26067607, 2015). "Thus, our results demonstrate that UBE3C may be a promising predictive biomarker for the poor prognosis of glioma, and may serve as an ideal therapeutic target for gliomas." (PMID 26067607, 2015). "Our results showed that 25 of the differentially expressed URGs were related to survival in glioma patients; six genes, CDC20, UBE3C, WDR62, DTL, HOXB4, and TRIM38, were statistically significant with an AUC value greater than 0.7." (PMID 33914773, 2021). "On the contrary, the ubiquitin-protein ligase E3C (UBE3C) led to the ubiquitination and degrading of Annexin A7, promoting glioma development." (PMID 34106407, 2021).
glioma (continued). "Our study clearly shows that high UBE3C expression contributes to glioma progression by ubiquitination and degradation of ANXA7, and thus presents a novel and promising target for future glioma therapies." (PMID 26067607, 2015). "Next, we evaluated the correlation between UBE3C and ANXA7 mRNA and protein expression in 12 cases of glioma tissues by linear correlation analysis." (PMID 26067607, 2015). "High levels of UBE3C were detected in 33 of the whole cohorts (33/80, 41.25%), and high UBE3C expression was more often detected in grade III and IV gliomas than in grade I and II gliomas." (PMID 26067607, 2015). "There was a statistically significant difference in UBE3C expression between glioma and non-tumor samples (p = 0.01)." (PMID 26067607, 2015). "Immunoreactivity of UBE3C protein was observed in the cytoplasm of glioblastoma tumor cells, and very low levels of UBE3C expression were detected in non-tumor tissues compared to glioma tissues." (PMID 26067607, 2015). "After the identification of primary gliomas using hematoxylin and eosin staining, UBE3C protein expression was investigated by IHC in glioma tissues and adjacent non-tumor tissues." (PMID 26067607, 2015). "This study demonstrates that UBE3C expression is upregulated in glioma tissues compared to normal tissues, and its overexpression promotes the invasion and mobility of glioblastoma cells." (PMID 26067607, 2015). "Our results also revealed that increased UBE3C expression was accompanied by a reduction in ANXA7 protein expression in glioma tissues, but not ANXA7 mRNA." (PMID 26067607, 2015). "In reciprocal co-IP assays, we showed that UBE3C formed a complex with ANXA7 in 293T cells, and the significantly negative correlation of both proteins in glioma samples." (PMID 26067607, 2015).
clear cell renal cell carcinoma (4 papers, 2022 to 2023). "Meanwhile, circPOLR2A interacts with UBE3C and PEBP1 proteins and promotes the UBE3C-mediated PEBP1 ubiquitination, thereby activating the ERK signaling pathway and facilitating clear cell renal cell carcinoma progression." (PMID 36895010, 2023).
gastric cancer (4 papers, 2021 to 2025). A primary or metastatic malignant neoplasm involving the stomach. "Accumulating evidence indicated that UBE3C is implicated in several tumors, including glioma, melanoma, renal cell carcinoma, hepatocellular carcinoma, breast cancer, lung cancer, and gastric cancer." (PMID 36825281, 2023). "And the role of UBE3C in gastric cancer has only recently begun to be explored." (PMID 36825281, 2023). "Previous studies have indicated the promoting roles of UBE3C in the malignant phenotype of tumor cells such as growth, proliferation, and dissemination in BRCA and gastric cancer, which were reportedly attributive to the activation of the oncogenic β-catenin." (PMID 37173692, 2023).
renal cell carcinoma (4 papers, 2015 to 2024). "Ubiquitin protein ligase E3C (UBE3C) was upregulated in renal cell carcinoma tissues and was reported to be associated with poor survival rate." (PMID 30577541, 2018). "For example, UBE3C gene expression was increased in renal cell carcinoma tissues compared with adjacent normal tissues." (PMID 33171965, 2020). "In renal cell carcinoma (RCC), circPOLR2A, regulated by YTHDF2 through m6A modification, enhances the interaction between PEBP1 and UBE3C." (PMID 39075555, 2024).
breast carcinoma (3 papers, 2021 to 2025). "LINC00963 can recruit Fosb to the ubiquitin protein ligase E3C (UBE3C) promoter and increase the radioresistance of breast cancer through UBE3C." (PMID 40821785, 2025). "The ubiquitin protein ligase E3C (UBE3C) has been reported to play an oncogenic role in breast cancer (BRCA)." (PMID 37173692, 2023). "Furthermore, to validate the correlation between UBE3C and radioresistance in breast cancer, we downloaded the radiotherapy transcriptome microarray dataset (GSE101920) of BRCA patients from the GEO database, in which we found that UBE3C was also significantly increased after radiation treatment." (PMID 37173692, 2023).
non-small cell lung carcinoma (3 papers, 2021 to 2022). A group of at least three distinct histological types of lung cancer, including non-small cell squamous cell carcinoma, adenocarcinoma, and large cell carcinoma. "UBE3C was described to be overexpressed in stem-like NSCLC (non-small-cell lung cancer) cells and acted as a stemness enhancer." (PMID 36497092, 2022). "In non small-cell lung cancer, UBE3C ubiquitinated and promoted AHNAK degradation, resulting in enhanced stemness." (PMID 34689136, 2021). "In non-small cell lung cancer (NSCLC) tissues, UBE3C maintains cancer stemness by ubiquitinating and promoting neuroblast differentiation-associated protein AHNAK (AHNAK) degradation." (PMID 35414786, 2022).
acute myeloid leukemia (2 papers, 2023 to 2025). Acute myeloid leukemia (AML) is a group of neoplasms arising from precursor cells committed to the myeloid cell-line differentiation. "A paradigmatic example is the balanced translocation involving UBE3C and MSI2, implicated in the pathogenesis of acute lymphoblastic leukemia (ALL) and aggressive acute myeloid leukemia (AML) subtypes, which can be precisely delineated by OGM." (PMID 41228238, 2025).
Angelman syndrome (2 papers, 2015 to 2020). A neurogenetic disorder characterized by severe intellectual deficit and distinct facial dysmorphic features. "Mutations in proteins involved in the UPS have been implicated in neurological disease (e.g., Ube3a in Angelman syndrome and Ube3c in autism spectrum disorders)." (PMID 26314864, 2015). "In this review article, we summarize recent findings on brain-expressed HECT-type E3 UBE3 ligases and their murine orthologues, comprising Angelman syndrome UBE3A, Kaufman oculocerebrofacial syndrome UBE3B and autism spectrum disorder-associated UBE3C." (PMID 33182779, 2020).
head and neck cancer (2 papers, 2024 to 2025). A primary or metastatic malignant neoplasm affecting the head and neck. "In head and neck cancers, pyrvinium pamoate has been shown to reduce UBE3C–LRP fusion gene-expressing tumor cell transformation via the degradation of β-catenin in a dose-dependent manner." (PMID 40940800, 2025). "LRP5 gene fusion with UBE3C results in the loss of the DKK-1 inhibitory domain; in a study of head and neck cancers, this fusion was found to stimulate Wnt/β-catenin signaling and upregulate MYC, CCND1, TCF4, and LEF13 expression, resulting in tumor cell proliferation." (PMID 40940800, 2025). "LRP5-UBE3C is an inter-chromosomal fusion transcript of LRP5 on chromosome 11q13.2 and UBE3C on chromosome 7q36.3 in the NT-8e cell line and six of head and neck cancer patients." (PMID 38438481, 2024). "In summary, our study presents the functional and clinical significance of a fusion transcript between the E3 ubiquitin ligase, UBE3C, and the Wnt signaling co-receptor, LRP5, found in a subset of patients with head and neck cancer." (PMID 38438481, 2024).
viral infection (2 papers, 2023 to 2024). "However, the role of UBE3C in different viral infections is still poorly understood, and more research is needed to discover its role and mechanism in viral replication." (PMID 39212385, 2024). "UBE3C has been reported to promote various types of ubiquitination, but it has not been reported during viral infection." (PMID 39212385, 2024).
asthma (1 paper, 2020). "Polymorphisms in UBE3C were identified as potent markers of nasal polyps and aspirin-intolerant asthma among Korean patients with asthma." (PMID 33171965, 2020).
basal cell carcinoma (1 paper, 2016). A carcinoma involving the basal cells. "Levels of UBE3C expression were much higher in primary and metastatic melanoma tissues than in normal skin, cutaneous squamous cell carcinoma or basal cell carcinoma." (PMID 26894856, 2016).
colon cancer (1 paper, 2025).
glioblastoma (1 paper, 2015). The most malignant astrocytic tumor (WHO grade IV). "To investigate the role of UBE3C in glioblastoma cells, we first evaluated UBE3C expression in SHG44, U251, U87, TJ861, and TJ899 cells by qRT-PCR and immunoblotting." (PMID 26067607, 2015). "Immunofluorescence also showed the co-localization of UBE3C and ANXA7 in glioblastoma cells." (PMID 26067607, 2015).
hepatocellular carcinoma (1 paper, 2020). A malignant tumor that arises from hepatocytes. "An exome analysis revealed frequent mutations of the UBE3C gene in human hepatocellular carcinoma." (PMID 33171965, 2020).
leukemia (1 paper, 2021). A malignant (clonal) hematologic disorder, involving hematopoietic stem cells and characterized by the presence of primitive or atypical myeloid or lymphoid cells in the bone marrow and the blood. "We evaluated the nuclear location of the chromosomal region surrounding MNX1 in the leukemia K562 cell line by FISH, and assessed the transcriptional activity of genes mapping in same region (i.e., LMBR1, NOM1, MNX1, UBE3C, and PTPRN2) by qRT-PCR." (PMID 33652823, 2021).
lung carcinoma (1 paper, 2025). "To further assess the functional interplay between SEC61G and UBE3C, we examined the effects of SEC61G expression changes on PGAM1 levels in lung cancer cell lines." (PMID 39990664, 2025).